SPRR3 (small proline rich protein 3)
Diseases named in the same sentence as SPRR3 in open-access papers (continued):
Sharing a sentence is not in itself a finding about the gene and the disease.
metastatic melanoma (1 paper, 2019). A melanoma that has spread from its primary site to another anatomic site. "Since SPRR3 belongs to a gene signature that can discriminate primary from metastatic melanoma, we herein suggest that ORF_CIN345 may promote melanomagenesis via perturbation of the SPRR-dependent cornification process." (PMID 30795533, 2019).
pterygium (1 paper, 2021). A wedge-shaped fibrovascular lesion arising from the bulbar conjunctiva and extending to the cornea. "An early microarray study identified SPRR3, SPRR1A, SPRR1B and IVL from the cornification subcategory as upregulated genes in pterygium." (PMID 34769520, 2021). "We added 4 of the top upregulated genes in pterygium: CLEC18A, FOSL1, PPMN1 and SPRR3." (PMID 34769520, 2021).
tumor (16 papers, 2012 to 2024). "It has been reported that SPRR3 is overexpressed in several tumor types, and is associated with tumor cell proliferation and invasion." (PMID 28938601, 2017). "Genes associated with tumor proliferation such as DSG2 and SPRR3 and genes related to energy metabolism process decreased along the invasion trajectory of the tumor, while the function of tumor progression-related gene BGN and metastasis growth-related gene POSTN gradually increased." (PMID 35899203, 2022). "At the interface between this zone and destained fully keratinized tumor cells with pyknotic nuclei, cells display variable morphology and strong SPRR3 expression." (PMID 39358322, 2024). "IF staining revealed the expression of cornification marker SPRR3 precisely at the interface between necrotic cysts and the vital tumor tissue." (PMID 39358322, 2024). "We used Oncomine datasets (Ye Head‐Neck, and Peng Head‐Neck) to verify the expression levels of KRT13, KRT78, and SPRR3 in HNSCC tumor and normal tissues." (PMID 37092360, 2023). "The strong staining of cystatin A, involucrin and SPRR3 was predominantly localized in the hyperkeratotic portion of tumor nests in well-differentiated ESCC tissues, but there was weak or negative staining in moderately- or poorly-differentiated ESCC tissues." (PMID 24796531, 2014). "Samples of the tumor immunohistochemical staining demonstrated that SPRR3 was highly expressed in tumors compared with the normal tissue." (PMID 24396461, 2014). "The SPRR3 has been reported as tumor suppressor in esophageal squamous carcinoma cells." (PMID 34065672, 2021). "As AKT signaling promotes tumor invasion, we used a Transwell invasion assay to measure cell invasiveness and the results demonstrated that the invasiveness of U251 cell lines significantly decreased following the knock down of SPRR3 expression." (PMID 24396461, 2014). "To further investigate KRT17 and SPRR3 as markers of HNSCC differentiation, we stained the original tumor tissue of P1 and P2 and HPV-negative tumor tissue of four additional patients with oropharyngeal and hypopharyngeal tumor location (P3-6)." (PMID 39358322, 2024). "Interestingly, the Ki-67 protein (MKI67)-expressing proliferative cancer cells were located at the tumor margin between LAMC2- and SPRR3-positive cells, further supporting the proliferative potential to differentiate into various mEpC types." (PMID 37853464, 2023). "There were also genes that are of insignificant expression in tumor cells that increase in expression in KO cells, e.g. THBS3, IL2RG, SPRR3, TGM2, HMOX1 and TMEM62 or are lower in expression in tumor cells and significantly decreased in KO cells such as MAN1A1, CES1, STCBP6, SIVA1 and TMEM40." (PMID 31797958, 2019). "Notably, in contrast to the findings in ESCC, in the present study, SPRR3 promoted GBM cell (U251) proliferation and invasion, and samples from the tumor immunohistochemical staining demonstrated that SPRR3 was highly expressed in the majority of tumors compared with the normal tissue." (PMID 24396461, 2014).
cancer (14 papers, 2012 to 2026). A tumor composed of atypical neoplastic, often pleomorphic cells that invade other tissues. "Enhanced expression of SPRR3 sensitizes cancer cells to loss of the mitochondrial outer membrane potential (MOMP) that leads to DNA damage-induced apoptosis." (PMID 31797958, 2019). "Loss of methylation also affected genes with cancer-related biological functions i.e. SPRR3, previously reported as hypomethylated in cancer, specifically in hepatocellular carcinoma." (PMID 23144874, 2012). "According to previous studies, SPRR3 can stimulate cell proliferation, whereas APOBEC3A can cause virus evolution and cancer mutagenesis by mediating the antiviral response, exerting a ‘second‐hit’‐like effect to accelerate disease escalation." (PMID 36967539, 2023). "For example, SPRR3, a member of the small proline-rich protein family, is under purifying selection in cancer cells (CN/CS = 0.27, p = 5.73 × 10–11, FDR = 1.91 × 10–8) and neutral selection in germline cells (pN/pS = 0.88, p = 0.75, FDR = 0.37)." (PMID 28938601, 2017). "cystatin A, involucrin and SPRR3 expression was significantly higher in carcinoma with well differentiation than that with moderate or poor differentiation (P = 0.002, P = 0.003 and P = 0.010, respectively)." (PMID 24796531, 2014).
inflammation (1 paper, 2023). Aberrant reaction of the microcirculation characterized by movement of fluid and leukocytes from the blood into extravascular tissues. "As one example of how this could have functional ramifications related to the impact of AUD on lung function, increased SPRR3 expression has previously been associated with lung inflammation." (PMID 37786945, 2023).
SPRR3 also shares sentences with these, for which no sentence is quoted: lung carcinoma (3 papers); adenocarcinoma (2); cardiovascular diseases (2); esophageal SCC (2); ischemic stroke (2); Stroke (2); acute pancreatitis (1); atopic dermatitis (1); autoimmune disease (1); bacterial infections (1); colorectal tumor (1); coronary artery atherosclerosis (1); dermatitis (1); gastric cancer (1); heart failure (1); hyperlipidemia (1); ichthyosis (1); infection (1); Insulin resistance (1); ischemia (1); ischemic heart disease (1); medulloblastoma (1); memory impairment (1); myocardial infarction (1); myocardial ischemia (1); neuroblastoma (1); Palmoplantar keratoderma (1); periodontitis (1); Pruritus (1); rheumatoid arthritis (1).
A further 3 diseases each share a sentence with SPRR3 in 1 paper.